MMP14 (matrix metallopeptidase 14)
Diseases named in the same sentence as MMP14 in open-access papers (continued):
Sharing a sentence is not in itself a finding about the gene and the disease.
tumor (continued). "EGF-like signaling ligands are also released by MMP14-mediated degradation of the laminin 5 γ2 chain to generate EGF-like fragments that drive EGFR signaling toward increased NSCLC tumor growth." (PMID 33014869, 2020). "Along the transition from M1 to M2 state, macrophages acquired features that promote tumor invasion, metastasis, and immunosuppression with upregulated genes like MMP14, VEGFA, and MRC1." (PMID 33298893, 2020). "In contrast to strong MMP14 expression in tumor-infiltrating GFP+ cells, GFP+ cells within normal brain were MMP14-negative (available online)." (PMID 31501884, 2020). "A small fraction of the tumors had elevated expression in nearly all tumor cells (staining score 3+), whereas most specimens had at least mild to moderate expression of MMP-14." (PMID 32848608, 2020). "Further study revealed that Twist1 binds to the promoters of MMP-2 and MMP-14 genes to regulate the tumor-suppressive effects of miR-539-5p." (PMID 32169087, 2020). "Correlation analysis between MMP14 and immune cell-related genes and markers, as assessed with Tumor Immune Estimation Resource (TIMER)." (PMID 32974187, 2020). "The strongest stimulus for invadopodia formation is, however, the mechanical stiffness of the ECM, and high collagen density stimulates the incorporation of MMP-14 into tumor cell invadopodia." (PMID 33379400, 2020). "The abundance and proteolytic activity of MMP-14 in the plasma and tumor secretions from VS patients correlated with clinical parameters and the degree of SNHL." (PMID 32848608, 2020). "In summary, this demonstrated an increased specificity of MMP14 expression in tumor-infiltrating hematopoietic cells." (PMID 31501884, 2020). "Only MMP2, MMP7 and MMP14 are shown to potentiate tumor growth and/or metastasis in multiple independent papers." (PMID 32325664, 2020). "A specific domain of the α3 chain of type IV collagen has anti-tumour effects through the inhibition of the expression of membrane-type 1-matrix metalloproteinase (MT1-MMP or MMP14) and integrin β3, which leads to impaired migratory abilities of tumour cells." (PMID 33037194, 2020). "It is possible that MMP14 at the invasive tumor front plays a dual role in cancer progression by deglycanating DCN and remodeling ECM to enable cancer cell invasion." (PMID 33317052, 2020). "On the other hand, these data show differential MMP‐14 gene expression between responders (n = 30) and non‐responders (n = 12) to RT, being this gene down‐regulated in radiosensitive tumours in the preoperative setting." (PMID 31568637, 2020). "There are at least 23 MMPs and four types of TIMPs expressed in humans, but MMP-2, MMP-9, MMP-14, TIMP-1, and TIMP-2 are often associated with the tumor invasion process." (PMID 32669083, 2020). "In this study, we only included the studies that examined the MMP-14 expression in tissues (tumor and paired normal tissues) by immunohistochemistry to ensure the reliability and consistency our results." (PMID 31956360, 2020). "We found that MMP14 expression was significantly correlated with RCC tumor T stage (p = 0.014), grade (p = 0.044), and pathologic stage (p = 0.025)." (PMID 32929380, 2020). "Our study provides insights for understanding the potential roles of MMP14 in tumor immunology and its suitability as a prognosis biomarker in DLBCL." (PMID 32974187, 2020). "In parallel, IHC analysis was applied to detect MMP14, E-cadherin, and N-cadherin protein levels in tumor tissues from each group." (PMID 32929380, 2020). "According to the expression and survival analysis, three genes (COL12A1, APOL1, and MMP14) were significantly higher in tumor samples when compared with normal controls and their upregulation indicated a poor prognosis." (PMID 33027767, 2020). "Within the tumor parenchyma, there were clusters of tumor cells that stained strongly positive for MMP-14." (PMID 32848608, 2020).
tumor (continued). "It has been proposed that MMP-14 plays a crucial role in pathological systems, such as tumor growth, invasion, and neovascularization." (PMID 31216704, 2019). "Circulating tumor cells adhering on the endothelial layer extend protrusions, which are rich in invadopodia markers MMP14, cortactin, Tks4, and Tks5." (PMID 31167468, 2019). "The prognostic DEmiRNA, hsa-miR-337-3p targeting one DEmRNA (AMOT, a witnessed oncogene in OSCC), has been implicated to target AMOT, HOXB7, MMP-14, PTEN and acted as a tumor suppressor through sponging oncogene." (PMID 31141819, 2019). "The theranostic nanoparticles disrupt the blood brain barrier in the tumor tissue through MMP-14 mediated activation of the VDA prodrug." (PMID 31723547, 2019). "MMP-14 expression in the tumor was twice as high as lung and liver and 3-4 times higher than in the kidney, heart, and spleen." (PMID 31723547, 2019). "In particular, MT1-MMP (MMP-14) is a zinc-dependent proteinase expressed in the cell membrane that is involved in the promotion of tumor growth and metastasis." (PMID 30700700, 2019). "LUM differs from FMOD in terms of cell interactive properties, being an MMP-14 inhibitor and it impedes tumor cell migration and growth through its interaction with α2β1 integrin which conveys anti-angiogenic properties." (PMID 30700002, 2019). "The combination of CLIO-ICT with ionizing radiation is particularly potent because CLIO-ICT is activated through an MMP-14-cleavable linker and thereby, only activated in the tumor tissue." (PMID 31723547, 2019). "IHC confirmed that MMP-14 protein levels in tumor regions of all GBM patient specimens were significantly (p < 0.001) higher compared to normal brain regions." (PMID 31723547, 2019). "Several proteins with ECM degradation activity, such as MMP-13, MMP14, and C4.4A have been found in exosomes and been demonstrated to involve in tumor migration and invasiveness." (PMID 30925935, 2019). "MMP14, a membrane-type, is present at high levels in the tumor cells themselves, while MMP9, a gelatinase specific to collagens IV and V, is more often upregulated in the stroma." (PMID 29996539, 2018). "An upregulation of either MMP9 or MMP14 in the stroma around the tumor cells is correlated with a more invasive phenotype, pointing to a critical role of MMPs in the tumor microenvironment." (PMID 29996539, 2018). "Given the known functions of MMP-14, it seems reasonable to suggest that inhibition of protease activity reduced the ability of stem cells to migrate from the primary tumor into the blood stream and from the blood stream into the stroma of the lungs and liver." (PMID 30034628, 2018). "Consistent with this premise is the higher expression of MMP-14 in and on cancer stem cells versus bulk tumor cells." (PMID 30034628, 2018). "As reported, MMP-2 and MMP-14 (MT1-MMP) are usually overexpressed in tumor cells, which play important roles in promoting cancer cell invasion and migration." (PMID 29250984, 2018). "This concentration injected is lower than has been used for efficacy studies of other monoclonal antibodies against MMP-14 and yet there was a highly significant impact on both primary tumor growth and, more importantly, on metastatic spread." (PMID 30034628, 2018). "The TIMP2-based protein displayed selective binding capacity to the tumor tissues via the interaction with MMP-14/MMP-2." (PMID 29250984, 2018). "Differential gene expression between responders (NR = 30) and non-responders (NNR = 12) was observed for APOA1, MAP3K4 and MMP14 genes with over 2-fold downregulation in pRT-responsive tumours." (PMID 30285791, 2018). "Strikingly, our data suggest that the presence of EDPs contributes to an enhanced invasiveness of these tumor cells by engaging matrix metalloprotease (MMP)‐14." (PMID 30186741, 2018). "To further explore the effect of targeting MMP-14 on tumor stem cells, we analyzed the expression of mesenchymal markers." (PMID 30034628, 2018).
tumor (continued). "Taken together, these results indicate that PROX1 binds to the MMP14 promoter and thereby negatively regulates its expression in human tumour cells." (PMID 29934628, 2018). "Although a reduction in the size of the primary tumor is good, the most dramatic and potentially clinically-relevant outcome of treatment with anti-MMP-14 IgG 3A2 was a 94% inhibition of metastasis to the lungs and livers." (PMID 30034628, 2018). "An MMP-14/CD44/Snail axis has been previously identified as an important regulator of tumor invasion in other tumors." (PMID 30034628, 2018). "Only 3 genes (APOA1, MAP3K4 and MMP14) were confirmed to be downregulated in radiosensitive tumours in the preoperative setting." (PMID 30285791, 2018). "FSCN1 and MMP14 are proteins that facilitate tumor progression and formation of a suitable tumor microenvironment." (PMID 30046565, 2018). "MMP-14 also has a central role in tumor invasion and not only degrades the ECM but also promotes the secretion of pro-MMP-2." (PMID 29358963, 2017). "MCTBP‐1 plays a role in the inhibition of promoting of tumor cell migration and invasion caused by membrane‐type 1 matrix metalloproteinase (MT1‐MMP/MMP‐14; Stipanuk, Simmons, Karplus, & Dominey, 2011)." (PMID 29043056, 2017). "Staining of tumor tissue sections revealed that MMP-14 blockade reduced the percentage of tumor cells positive for the proliferation marker Ki67." (PMID 28938563, 2017). "This included more anti-tumor immune profiles, including increased density of iNOS+ cells and Granzyme B+ cells with MMP-14 blockade." (PMID 28938563, 2017). "In mammary orthotopic tumor xenograft assays, MMP-14 blockade by IgG 3369 limited tumor growth and metastasis." (PMID 28938563, 2017). "The association of CAIX with MMP14 is a particularly interesting finding since MMP14 is a cell surface metalloprotease involved in matrix degradation, tumor cell invasion and metastasis." (PMID 28692057, 2017). "Together, these results demonstrate that 4T1 tumor growth, hypoxia and metastasis are limited upon MMP-14 blockade." (PMID 28938563, 2017). "It has been reported by many researchers that MMP14 has played a crucial role in tumor growth and migration process of EMT dependence." (PMID 29050340, 2017). "To more comprehensively profile the effects of MMP-14 blockade on anti-tumor immunity, we used the syngeneic model of 4T1 cell engraftment in the mammary fat pad of Balb-c mice." (PMID 28938563, 2017). "The mode of action for our MMP-14 inhibitory antibody is consistent with disruption of MMP-14 effects on tumor angiogenesis, hypoxia, immune suppression, and metastasis." (PMID 28938563, 2017). "Analysis of tumor tissue sections revealed that MMP-14 blockade limited tumor neoangiogenesis and hypoxia." (PMID 28938563, 2017). "Although MMP14 has been studied in a number of tumor cases and has long been considered it was correlated with EMT and featured with a capacity of enhancing cell invasion and migration, little is known about its significances in IPF." (PMID 29050340, 2017). "Expression levels of miR‐34a and target genes AXL and MMP14 are closely correlated among each other and clearly separate tumor from adjacent normal tissue." (PMID 28596300, 2017). "MMP-14 is frequently overexpressed in cancer and has been shown to play a critical role in tumor growth and metastasis." (PMID 27531896, 2016). "The aggressive behavior of SCCs is illustrated by the fact that MMP-14 is expressed at the surface of tumor cells." (PMID 27271600, 2016). "The magnitude of the correlations between the presence of MMP-14 in the tumour epithelium and MMP-14 in the tumour stroma indicate a strong effect." (PMID 27038607, 2016). "Both stromal fibroblasts and tumor cells in SCC, particularly at the invasive front of the tumor, secrete MMP-14." (PMID 27271600, 2016).
tumor (continued). "In our cohort, high MMP-14 expression was found in two thirds of early-stage tumours whereas in the advanced-stage group only in half of the tumours high expression was found." (PMID 27038607, 2016). "MMP14 enhances tumor invasion and dissemination through cleavage of CD44, a cell surface glycoprotein, or activation of MMP-2 and MMP9 through a combination of TIMP-2 and MMP14." (PMID 27613828, 2016). "In line with the mRNA studies this analysis revealed a higher geometric mean value, thus a higher abundance, for Mmp14 at the surface of TICs compared to non-CD24+CD90+ tumor cells." (PMID 27542270, 2016). "As a member of MMP family, MMP14 plays a vital role in the growth, migration, invasion and angiogenesis of tumor cells." (PMID 27613828, 2016). "Correspondingly, NIK increases the phosphorylation, enzymatic activity and pseudopodial localization of membrane type-1 matrix metalloproteinase (MT1-MMP/MMP14), which is associated with enhanced tumor cell invasion of three-dimensional collagen matrices." (PMID 27270613, 2016). "MiR-22 suppressed tumor invasion and metastasis by targeting member matrix metalloproteinase 14 (MMP14) and Snail." (PMID 27564100, 2016). "MMP-14 is expressed both in the tumor epithelium and in the stroma, whereas E-cadherin is only expressed in the tumor epithelium." (PMID 27590006, 2016). "We further demonstrated that miR-22 acted as tumor suppressors through targeting extracellular matrix (ECM) remodeling member matrix metalloproteinase 14 (MMP14) and epithelial-to-mesenchymal transition (EMT) inducer Snail in GC." (PMID 26610210, 2015). "Previous studies have indicated that MMP-14 promotes the tumor invasion by functioning as a pericellular collagenase and an activator of proMMP-2, and is directly linked to tumorigenesis and aggressiveness." (PMID 26084291, 2015). "Hes1 mRNA expression and MMP14 mRNA expression were positively correlated in tumor tissue (correlation coefficiency = 0.238, p = 0.035)." (PMID 26650241, 2015). "For example, a potent and highly selective humanized antibody inhibitor of MMP14 activity, DX-2400, blocked tumor growth in mouse models of breast and liver carcinogenesis, without causing overt toxicity as has been observed with other MMP inhibitors." (PMID 26046767, 2015). "Since previous studies indicate that MMP-14 promotes the growth, migration, invasion, and angiogenesis of tumor cells, we further investigated the effects of miR-337-3p over-expression and MMP-14 restoration on cultured NB cells." (PMID 26084291, 2015). "It is probable that the upregulation of MMP14 or Snail by suppression of miR-22 contributed to tumor progression in GC." (PMID 26610210, 2015). "The fact that restoration of MMP-14 was sufficient to prevent the NB cells from miR-337-3p-inhibited biological behaviors indicates that miR-337-3p exerts its tumor suppressive functions, at least in part, through repressing the MMP-14 expression in NB." (PMID 26084291, 2015). "Several genes that are implicated in angiogenesis (Vegfa, Hgf), suppression of immunity (Arg1, Tgfb3), and tumor invasion (Mmp2, Mmp14, Ctgf) were also highly expressed in our GAMs data set." (PMID 25658639, 2015). "That is, VEGF is the molecule mediating the synergistic effects of semaphorin-3A and MMP-14 on tumor progression and metastasis." (PMID 24765144, 2014). "Immunostaining of MMP9 and MMP14 in the tumor tissues were both inversely correlated with miR-34a expression measured by qRT-PCR." (PMID 25268950, 2014). "MMP9 and MMP14, which have been regarded as regulators of tumor migration and invasion, are known to be involved in cell migration and invasion and frequently found to be upregulated in HNSCC." (PMID 25268950, 2014).
tumor (continued). "In the late phase of HA-CD44 binding, the CD44 at the leading edge of the cell is cleaved by a disintegrin and metalloproteinase domain (ADAM) protein and matrix metalloproteinase 14 (MMP14), and this cleavage is required for tumor cell migration." (PMID 24410905, 2014). "Some MMPs, like MMP-2, MMP-9, and MMP-14, can act both as positive and negative regulators of angiogenesis in tumor vasculature." (PMID 24578639, 2014). "Semphorin-3A can induce tumor cell migration by reducing MMP-14 secretion and thus regulate ECM degradation." (PMID 24765144, 2014). "These cells had malignant potential, with an increased expression of matrix metalloproteinase-14 (MMP-14), leading to tumor emboli within pulmonary arteries in in vivo studies." (PMID 24489925, 2014). "The abnormal expression levels of semaphorin-3A and MMP-14 appear to promote tumor cell proliferation, which provides direct evidence for its damaging impact on tumor progression and disease prognosis." (PMID 24765144, 2014). "Compared to the cells transduced with scrambled shRNA, we observed that silencing of MMP14 inhibited the proliferation of tumor cells when treated with TMZ or XRT alone, as well as in combination." (PMID 24156018, 2013). "Among the MMP family proteases, membrane type-1 MMP (MT1-MMP; also called MMP-14) is essential for the peri-cellular proteolysis of collagen matrix in the basement membrane, as well as tumor cell invasion and metastasis." (PMID 23516511, 2013). "Conversely, lumican can be degraded by MMP-14, revoking its anti-tumor properties which depend on intact native molecule." (PMID 24098450, 2013). "Clinical evidence has shown the linkage between high MMP-14 expression and cancer progression, such as lymph node metastases, invasion, poor clinical stage, larger tumor size, and increasing tumor stage." (PMID 23394613, 2013). "Intracellular signaling transduction pathways are often exploited during tumor invasion and migration and the involvement of β-catenin and MMP14 in the Wnt signaling transduction pathway has been identified to accelerate tumor invasion and migration." (PMID 24137406, 2013). "In the present study, EC cells transfected with DKK1 siRNA showed increased tumor cell invasion and migration when compared with the untreated and control-treated cells, indicating an upregulation of β-catenin and MMP14." (PMID 24137406, 2013). "MT1-MMP (MMP14) plays a critical role in the process of cell motility and invasion, with its deletion in tumor cells resulting in the loss of both in vitro and in vivo invasive activity." (PMID 24180670, 2013). "An inhibitory human antibody targeting MMP-14, developed using phage display technology, has shown in vivo activity in mouse xenograft tumor models." (PMID 23185522, 2012). "On the other hand, lumican (and decorin) can be degraded by MMP-14, abrogating the anti-tumour effect of these proteins." (PMID 23236386, 2012). "MMP-2, MMP-9, and MMP-14 have been reported to be involved in tumor angiogenesis and extracellular matrix remodeling." (PMID 22496834, 2012). "MT1-MMP, also known as MMP-14, has a single transmembrane domain and is an integral membrane protein with an extracellular catalytic domain suggested to be a key enzyme in tumor metastasis and angiogenesis." (PMID 22242160, 2012). "The matrix metalloproteinase MMP14 is known to participate in tumor metastasis and is the subject of intense research activity, making this a high-value target in OS and ASPS." (PMID 23251904, 2012). "Retroviral insertions were present in the mouse homologs of 10 genes tagged in the zebrafish tumor samples: Brd2, Cirbp, Fgf8, Hexim1, Map2k5, Mmp14, Ncoa2, Slc30a5, Sox4, and Sox5." (PMID 21533036, 2011). "MMP-14 immunostaining in primary tumor specimens is a prognostic predictor in patients with medullary thyroid carcinomas or carcinoma of the larynx." (PMID 21152183, 2011).